IL10 (interleukin 10)
Diseases named in the same sentence as IL10 in open-access papers (continued):
Sharing a sentence is not in itself a finding about the gene and the disease.
colitis (continued). "TLR4 dependent signaling of LPS derived from MDR PA differentially mediates both intestinal and splenic immune responses in murine chronic IL10−/− colitis." (PMID 29151895, 2017). "Treg cells have been shown to suppress immune responses in humans and inhibit colitis through IL-10 production." (PMID 28400554, 2017). "In IL-10 gene disrupted mice, experimental colitis is also characterized by reduced GHR expression in the liver driven by TNF-α-induced reduction in nuclear SP3." (PMID 28486400, 2017). "For instance; IL-10−/− mice develop spontaneous colitis that is characterized by histological findings similar to those of human IBD." (PMID 28484453, 2017). "In the present study, we showed that in contrast to the state of TLR6−/− mice, DSS-induced colitis induced the production of pro- and anti-inflammatory cytokines, including IL-10, in TLR1−/− mice." (PMID 28289440, 2017). "Animal models, including trinitrobenzene sulfonic acid (TNBS)-induced experimental colitis, dextran sulfate salt (DSS)-induced colitis, and a number of genetic mouse models (such as IL-10−/−), have been established to study the underlying mechanisms." (PMID 29270177, 2017). "IL-37b-tg mice protect from DSS-induced colitis, characterized by decreasing clinical disease score, histological score, and TNFα and IL-1β production, but increasing IL-10 production in colon tissue." (PMID 28420941, 2017). "We used IL-10 k.o. mice with piroxicam accelerated colitis (PAC), to evaluate the influence of active colonic inflammation on GHR expression in vivo (see experimental setup #1 in Section 4.6)." (PMID 28946616, 2017). "Of the remaining miRNAs, miR-199a-3p was down-regulated in DSS induced colitis (and the IL10−/− model), but it was unaltered in the TLR5−/− model." (PMID 28566745, 2017). "Female IL10−/− mice were monitored for colitis development for 98 days, from weaning at day 30 (D30) to 98 days post-weaning (D98)." (PMID 28566745, 2017). "Macroscopic and histological scores were evaluated after 6 weeks, when IL-10−/− mice show the signals of spontaneous colitis." (PMID 28194152, 2017). "In the development of colitis in IL-10−/− mice, higher levels of a Barnesiella phylotype correlated with lower activity levels of the disease." (PMID 29232851, 2017). "An increase in Treg-associated FoxP3 and anti-inflammatory cytokines IL-10 and TGF-β expression in the MLNs during trinitrobenzene sulfonic acid (TNBS) colitis was also observed." (PMID 33525778, 2017). "The expression of IL-10 mRNA was significantly higher in the colons of p85α+/− BMDM-transferred colitis mice than those of WT BMDM-transferred colitis mice." (PMID 28733636, 2017). "In an interleukin-10 (IL-10) gene-deficient murine model of IBD, infection by Heligmosomoides polygyrus was evaluated for treatment of colitis, and indeed, the amelioration of colonic inflammation was observed in wild-type C57BL/6 mice." (PMID 29095820, 2017). "Reduces inflammation in a mouse model of DSS-induced colitis, probably by increasing the expression of anti-inflammatory cytokines (IL-10 and TGF-β) and reducing pro-inflammatory ones (IL-6 and TNF-α)." (PMID 29163443, 2017). "Adoptive transfer of HD-DCs suppresses DNBS-induced colitis, with the greatest benefit occurring in those mice showing significant increases in IL-10 and IL-4 production by splenic T cells." (PMID 28094779, 2017). "Strains inducing high levels of the regulatory cytokine interleukin 10 (IL10) in human peripheral blood mononuclear cells (PBMCs) were the most effective at alleviating TNBS-induced-colitis." (PMID 28505101, 2017). "Pretreatment with niacin normalize IL-10 level in the colon of rats with iodoacetamide-induced colitis." (PMID 28769047, 2017). "In the spontaneous colitis model using IL-10 knockout mice, GH showed a positive effect on colon histology and significantly reduced epithelial apoptosis possibly by increasing expression of the anti-apoptotic BCL-2." (PMID 28486400, 2017).
colitis (continued). "To confirm the usefulness of the IL10−/− model as a tool for investigating miRNA expression profiles during intestinal inflammation, we characterized the development of colitis in these mice." (PMID 28566745, 2017). "This parallels the mouse phenotype, as IL-10 knockout mice are sensitive to the spontaneous development of colitis." (PMID 27795299, 2017). "A recent publication also showed that BF-PSA enhanced the production of IL-10 in a trinitrobenzene sulfonic acid-colitis mouse model." (PMID 28683149, 2017). "The colonic level of anti-inflammatory cytokine IL-10 was, however, reduced in colitis rats, an effect that tended to be prevented by niacin." (PMID 28769047, 2017). "So, while circulating TNFα and IL-17 levels seem to correlate with the DSS colitis clinical course, IL-1β, and IL-10 mainly correlate with the histological damage that tends to become chronic." (PMID 26973525, 2016). "On the contrary, two recent papers by Hausmann's group showed that, after metabolism to Cer, dietary SM triggers apoptosis in murine IECs and aggravates intestinal inflammation in acute DSS-induced colitis and in IL-10 knockout mice." (PMID 26880864, 2016). "CD8+ T cells cultured in the presence of IL-4 acquire an IL-10-producing phenotype and after adoptive transfer, these cells are capable of amelioration of colitis." (PMID 26908454, 2016). "Treg cells are known as a major source of IL-10 and have anti-inflammatory effects on the development of colitis." (PMID 27438072, 2016). "In our previous characterization of the Nlrp3−/− mice, we reported that these mice exhibited reduced colonic IL-10 expression during the inflammatory phase of DSS-induced colitis." (PMID 27610005, 2016). "Here we found that CD11b deficient (Itgam−/−) mice were more susceptible to dextran sulfate sodium (DSS)-induced colitis, with more tumor necrosis factor α (TNF-α) while less IL-10 production." (PMID 27188220, 2016). "Simultaneously, Foxp3+ Treg require IL-10 signals to maintain their regulatory function to prevent colitis." (PMID 27027442, 2016). "Here we investigated the role of Lcn2/NGAL in intestinal inflammation using a spontaneous mouse colitis model, interleukin-10 knock out (IL-10 KO) mice." (PMID 27734904, 2016). "Taken together, these data provide hints about how IL-10 KO Treg-of-B cells utilize other regulatory pathways to attenuate the severity of colitis." (PMID 27581189, 2016). "Treg-of-B cells inhibited colitis and suppressed Th1 and Th17 responses in an IL-10-independent manner." (PMID 27581189, 2016). "Early studies demonstrated that IL-10−/− mice spontaneously develop colitis, and a more recent study showed that the development of colitis requires microbial stimulation." (PMID 27973396, 2016). "In an SPF environment Il10−/− mice develop minimal intestinal inflammation, while colonization with the intestinal pathogen Helicobacter hepaticus elicits severe colitis, demonstrating that specific microbial antigens are pivotal for disease development." (PMID 27027442, 2016). "Treating these mice with neutralizing antibodies against TNFα and IL-10 ameliorated colitis severity and prolonged survival." (PMID 27997590, 2016). "On the other hand, mice with defective IL-10 signaling in intestinal macrophages develop spontaneous colitis when bred in a Helicobacter-positive facility, but are free of spontaneous colonic inflammation if Helicobacter spp." (PMID 27027442, 2016). "In the original paper, the reconstitution of SCID mice with naive CD4+ T cells and OVA-specific CD4+IL-10+ T cell clones resulted in prevention of colitis." (PMID 27683580, 2016). "The DSS colitis model has been characterized by increased serum levels of IL-6, IL-17, and TNFα and elevated levels of IL-4, IL-6, IL-10 and IFNγ have been reported in chronic colitis." (PMID 27177331, 2016). "These CD8+ T cells inhibited the activation and differentiation of inflammatory CD4+ T cells via IL-10 expression in the colitis model." (PMID 26908454, 2016).
colitis (continued). "We further examined the contribution of IL-10 to the anti-inflammatory effect of MS in the DSS-induced colitis model." (PMID 27405597, 2016). "Then we found less IL-10 in serum of Itgam−/− mice after DSS induced colitis than their littermate control." (PMID 27188220, 2016). "In conclusion, the preventive administration of E. durans TN-3 suppressed the development of DSS colitis via the induction of IL-10 producing Treg cells by restoring of the diversity of gut microbiota." (PMID 27438072, 2016). "In conclusion, Treg-of-B cells protected against experimental colitis through an IL-10-independent mechanism." (PMID 27581189, 2016). "Restoring Lcn2 expression in intestinal macrophages by transfer of IL-10KO-derived TEPMs attenuated colitis in 4-week-old Lcn2/IL-10 DKO mice." (PMID 27734904, 2016). "Plasma levels of IL-10 and the IL-10/IL-12 ratio were higher in the butyrate group than in the colitis group, but IL-12 levels were lower." (PMID 27473867, 2016). "Lcn2/IL-10 double-KO mice showed a more rapid onset and development of colitis compared to IL-10 KO mice." (PMID 27734904, 2016). "Our results indicate that sodium butyrate protects against colitis, possibly through modifying the gut microbiota, enriching biodiversity and reducing the amount of colitogenic IgA-coated bacteria in IL-10−/− mice." (PMID 27886121, 2016). "IL-10−/− mice developed spontaneous, progressive colitis, which eventually affected the small intestine as well." (PMID 26908454, 2016). "Recently, an Ancanthocheilonema viteae derived immunomodulatory was shown to induce macrophages with high levels of expression of IL-10 and PD-L1 capable of reducing signs of colitis in mice after cell transfer." (PMID 27806135, 2016). "The mRNA expression of IL-10 also decreased in the colon of Itgam−/− mice after DSS induced colitis compared with their littermate control." (PMID 27188220, 2016). "Our findings are consistent with a report by Murai and colleagues showing that secretion of IL-10 by myeloid cells helps maintain Foxp3+ Tregs in a model of colitis." (PMID 26756215, 2016). "In the mouse-TNBS colitis model, oral administration of Imm124E increased serum levels of the anti-inflammatory cytokine IL-10 and promoted both CD4+CD25+ and CD4+Foxp3+ Tregs." (PMID 26900473, 2016). "Transfer of Lcn2-repleted macrophages prevented the development of colitis in Lcn2/IL-10 double-KO mice in vivo." (PMID 27734904, 2016). "In summary, our data provide evidence that oral treatment with sodium butyrate protects against colitis, possibly through reducing the amount of colitogenic IgA-coated bacteria and modifying gut microbiota in IL-10−/− mice." (PMID 27886121, 2016). "Genetic ablation of IL-10 or IL-10R leads to spontaneous colitis in mice, representing a reliable model for human IBD." (PMID 27611574, 2016). "Since splenic and PerC CD5+ B cells are protective against colitis, we examined the relative production levels of the anti-inflammatory cytokine IL-10 in TLR-stimulated colonic LP CD5+ and CD5- B cells in vitro." (PMID 26727001, 2016). "Later on, several other groups confirmed the antigen-specific suppressive potential of CD4+IL-10+ T cells in vivo using colitis, experimental autoimmune encephalomyelitis (EAE), collagen-induced arthritis, and allergy disease models." (PMID 27683580, 2016). "Baseline IL-17 level was significantly associated with the later development of severe diarrhea/colitis while the combination of baseline TGF- β1 and IL-10 levels were associated with therapeutic clinical outcome after neoadjuvant ipilimumab." (PMID 26380086, 2015). "Gut microbiota and associated endotoxin are major sources of stimulation that promote inflammation and spontaneous colitis in Il10−/− mice." (PMID 26412089, 2015). "For this we used a well-described model of colitis following Helicobacter hepaticus (Hh) infection and concomitant blockade of the IL-10-IL-10R pathway." (PMID 26200014, 2015).
colitis (continued). "In an experimental model of TNBS-induced colitis, Foligne at al. demonstrated that probiotic strains with high IL-10/IL-12 ratio in vitro provided the best protection in vivo." (PMID 26218526, 2015). "Supporting these findings, the immunomodulatory effect of a polysaccharide A from Bacteroides fragilis was directly correlated with TLR2-signalling and increased FoxP3+Treg cells secreting IL-10 in an experimental model of TNBS-induced colitis." (PMID 25853847, 2015). "In the same study, inhibition of colitis development was also evident when a GILZ fusion protein was administered to DNBS-treated wildtype (WT) animals and IL-10 knockout mice with fully developed colitis." (PMID 26498359, 2015). "In order to test the functions of the IL-10-expressing Mos in vivo, we created a colitis model in the present study." (PMID 25588622, 2015). "Another way to study probiotic efficiency in reducing the prevalence of CRC is the IL-10 KO mice model, leading to spontaneous colitis and colon cancer development." (PMID 25741323, 2015). "Intestinal SLC26A3 mRNA has been reported to be downregulated in ulcerative colitis and in the IL10 transgenic colitis model, but SLC26A3 protein levels in intestinal tissues of patients with ulcerative colitis were unchanged." (PMID 26157392, 2015). "While IL-10 production by macrophages is dispensable for progression of colitis, IL-10R signaling in macrophages is critically involved in controlling the progression of autoimmune colitis in mice." (PMID 26412089, 2015). "This suggests that pharmacodynamics of IL-10 are subtle and potentially needs a sustained and more mucosa-focused delivery to be efficient against colitis." (PMID 25889561, 2015). "IL-10 is an important anti-inflammatory cytokine that regulate the colonic inflammation during experimental colitis in the presence of microbiota." (PMID 26697117, 2015). "The IL-10−/− mouse – incapable of producing the anti-inflammatory cytokine IL-10 – is the best-studied model of colitis." (PMID 26635787, 2015). "Relevant to this point, it has been reported that intragastric administration of IL-10-producing recombinant Lactococcus lactis reduced colitis in DSS-treated or IL-10-/- mice." (PMID 26218526, 2015). "In the present study, we investigated the role of OPN in the development of colitis using a murine experimental colitis model: interleukin-10 knockout (IL-10 KO) mice that develop spontaneous colitis in response to enteric bacteria." (PMID 26274807, 2015). "OPN/IL-10 DKO mice rapidly developed colitis within 1 week, however, and had increased infiltrating immune cells and remarkable epithelial hyperplasia in the rectum compared to IL-10 KO mice at 4 weeks of age." (PMID 26274807, 2015). "Histochemical examination revealed the initiation of colitis between 3 and 4 weeks of age in both IL-10 KO and OPN/IL-10 DKO mice." (PMID 26274807, 2015). "Local treatment with IL-10-secreting Lactococcus lactis (L. lactis) prevented the development of colitis in IL-10 KO mice and reduced inflammation in the DSS-induced mouse model of colitis without systemic side effects." (PMID 26199463, 2015). "In this regard, the rapidly deteriorating colitis in OPN/IL-10 DKO mice cannot be completely explained by the effect of sOPN deficiency on macrophage cytokine production." (PMID 26274807, 2015). "In line with these pioneer works, our studies also demonstrate that IL-10-producing Mos can inhibit the experimental colitis." (PMID 25588622, 2015). "Treatment with HBO normalized IL-1β, TNF-α, CINC-1 and IL-10 (P < 0.05) in rats subjected to colitis by TNBS." (PMID 25926972, 2015). "PUA was also identified to ameliorate DSS-induced colitis and spontaneous pan-enteritis in IL-10−/− mice." (PMID 26714018, 2015). "A notable example is that of mice defective in IL-10 and TGFβR2 signaling develop spontaneous colitis in response to commensals." (PMID 25741691, 2015).
colitis (continued). "Compared to untreated colitis, both oral fucoidan extracts significantly lowered the levels of IL-1α, IL-1β, IL-10, MIP-1α, MIP-1β, G-CSF and GM-CSF." (PMID 26083103, 2015). "Even though it is protective factors in colitis, with suppressive functions through IL-10 and FOXP3." (PMID 25651850, 2015). "In the present study, however, OPN/IL-10 DKO mice had accelerated colitis compared to IL-10 KO mice, suggesting that OPN deficiency is a detrimental factor in the onset of spontaneous colitis." (PMID 26274807, 2015). "Consistent with this, T cell-specific or FoxP3+ Treg-specific deletion of Il10 results in spontaneous colitis, highlighting the importance of Treg-derived IL-10 in preventing intestinal inflammation." (PMID 25944983, 2015). "More particularly, the use of recombinant L. lactis secreting IL-10 for the prevention and treatment of colitis in different mouse models has been largely studied." (PMID 25889561, 2015). "Next, we investigated the effect of OPN on macrophages, which are deeply involved in the initiation of colitis in IL-10 KO mice by sensing luminal bacterial components and producing a variety of pro-inflammatory cytokines." (PMID 26274807, 2015). "Analysis of different classes of antibiotics indicated differential and localized roles of bacteria species in the establishment and perpetuation of colitis in IL-10−/− mice after colonization with SPF bacteria." (PMID 24616886, 2014). "Compared with the control group, plasma levels of IL-12 and IL-23 in the colitis group were significantly higher (P <0.05; Figures 2Band 2D), and the IL-10 levels and IL-10/IL-12 ratio in the colitis group were significantly lower." (PMID 25275569, 2014). "In proof-of-concept experiments, we showed that salubrinal, which inhibits the PP1c/GADD34 activity, restored the eIF2α phosphorylation and prevented colitis in IL10/Nox1dKO mice." (PMID 25014110, 2014). "IL10/Nox1dKO mice (n = 150) spontaneously developed clinical signs of colitis from 6–7 weeks of age and disease activity index (DAI) scores worsened with age." (PMID 25014110, 2014). "Oral administration of B2 DNA beads significantly improved body weight, reduced colon injury, and suppressed colonic and circulating cytokine levels in mice with spontaneous colitis (IL-10 knockout) and with dextran sulfate sodium-induced colitis." (PMID 25127031, 2014). "When administered orally, these DNA beads improves body weight, reduces colon injury and suppresses colonic and circulating cytokine levels in mice with spontaneous colitis (IL-10 knockout mice) or with dextran sulfate sodium-induced colitis." (PMID 25127031, 2014). "On the protein level, ELISA analysis of colon supernatants demonstrated increased concentrations of IFN-γ, IL-17A and IL-10 in the colons of mice with colitis." (PMID 25313594, 2014). "IL-10−/− mice spontaneously developed colitis, characterized by prominent epithelial hyperplasia with leukocyte infiltration into the liver." (PMID 24392145, 2014). "The development of colonic inflammation in IL-10 knockout mice was accompanied by the upregulation of miR-101, miR-223 and miR-146a." (PMID 25323448, 2014). "Plasma levels of IL-10 and the IL-10/IL-12 ratio in the supernatant group were greater compared with those in the colitis group (P <0.05)." (PMID 25275569, 2014). "IL-10-deficient mice are highly prone to chronic colitis and genomically-controlled human IL-10 expression rescued Il10−/− mice from Helicobacter-induced colitis." (PMID 25475342, 2014). "The effectiveness of this DNA delivery system was demonstrated previously in healthy mice that received LL-FnBPA-GFP and also in a TNBS-induced colitis mouse model, where the delivery of IL-10 DNA was evaluated using LL-FnBPA-IL10." (PMID 25249337, 2014). "The Macrophage galactose-type lectin-1 (MGL1) plays a regulatory role in murine colitis as it contributes to IL-10 secretion by lamina propria macrophages upon interaction with invading commensal bacteria." (PMID 25068517, 2014).